CD4 (CD4 molecule)
Diseases named in the same sentence as CD4 in open-access papers (continued):
Sharing a sentence is not in itself a finding about the gene and the disease.
rheumatoid arthritis (continued). "In rheumatoid arthritis patients, chronic exposure of total T cells to TNFα impairs cell-mediated immune responses via CD28 downregulation whereas memory CD4+CD45RO+ T cells acquire a stronger Th17 pathogenic profile compared to cells from healthy donors under Th17-polarizing conditions." (PMID 35216459, 2022). "Similarly, among inflammatory cells involved in rheumatoid arthritis (RA), macrophages and CD4+ Tems play a key role, which keeps in line with the current study." (PMID 35589692, 2022). "Indeed, CD4+CD28− T lymphocytes isolated from rheumatoid arthritis patients show a preferential polarization towards the Th17 phenotype with expression of the transcription factor RORγt." (PMID 35269683, 2022). "TPH cells are a recently reported novel subpopulation of CD4+ helper T cells, which induce the differentiation of B cells into antibody-secreting cells and were identified in the peripheral blood and synovial tissues of rheumatoid arthritis patients." (PMID 34991631, 2022). "This increase may be related to the good results obtained for autonomy and sensory parameters because studies have shown that high levels of CD4+ and CD8+ TIM3+ T cells are inversely associated with the evolution of rheumatoid arthritis." (PMID 36193083, 2022). "Also, CD4+CD28- T lymphocytes isolated from the synovial fluid of rheumatoid arthritis-affected patients were capable of producing higher levels of IL-17A as compared with isolated CD4+CD28+ T lymphocytes." (PMID 34341698, 2021). "Moreover, rheumatoid arthritis patients have higher levels of CD4+PD-1+CXCR5+ Tfh cells in peripheral blood than healthy controls, and the frequency of CD4+ICOS+CXCR5+ Tfh cells is linked with DBA/1 mice undergoing CIA." (PMID 34203838, 2021). "Finally, in our previous research, we found that DNA methylation of CD4+ cells in rheumatoid arthritis showed abnormal DNA methylation in HLA regions." (PMID 34777472, 2021). "Additionally, IL-1RII expression is dysregulated in CD4+ T cells from patients with rheumatoid arthritis." (PMID 33507149, 2021). "Also, serum levels of survivin-WT in active rheumatoid arthritis patients and healthy controls were similar in CD4 + and CD19 + cells, while survivin-2B and -ΔEx3 were significantly higher in CD19 + B cells." (PMID 33441606, 2021). "In addition, substantial amounts of inflammatory cytokines (INF-γ, IL-17, and TNF-α) from CD4+ T-cells were abundantly augmented due to upregulated expression of calcium-release-activated calcium channels in patients with rheumatoid arthritis." (PMID 34639190, 2021). "A CXCL13‐producing CD4 T‐cell subset was reported in rheumatoid arthritis." (PMID 33943020, 2021). "Similarly CD4+ T cells from patients with rheumatoid arthritis (RA) divert glucose into the PPP to increase NADPH production for protection against ROS." (PMID 32812866, 2020). "For instance, rheumatoid arthritis (RA) patients exhibit memory CD4+ T cells specific for various citrullinated antigens, including citrullinated aggrecan and citrullinated vimentin, which correspond to autoantibodies directed against citrullinated antigens and proteins in these patients." (PMID 32106536, 2020). "We initially hypothesized that Mir223 deficiency may ameliorate lupus nephritis since MIR223 is overexpressed in CD4+ T cells in the patients with relapsing multiple sclerosis and rheumatoid arthritis." (PMID 33574820, 2020). "Indeed, circulating CD4 T cells from patients with rheumatoid arthritis show higher expression of PD-1 than those from HC." (PMID 32223753, 2020). "In addition to this decreased expression, a delayed recruitment of SHP1 to the IS has been shown in CD4+ T cells of rheumatoid arthritis (RA) patients, a defect promoting T cell hyper-activation." (PMID 31297117, 2019).
rheumatoid arthritis (continued). "Recently, a novel population of CXCR5−PD-1hi CD4+ T cells, coined peripheral T helper (Tph) cells, was shown to be strongly expanded both in the synovium and in the peripheral blood of individuals with seropositive rheumatoid arthritis." (PMID 31270583, 2019). "In humans, the proportion of CD4+ T-cells that also express CCR5 varies according to tissue source and inflamation; approximately 5–10% of peripheral blood CD4+ T-cells express CCR5, while most gut associated lymphoid tissue and rheumatoid arthritis synovial fluid CD4+ T-cells are CCR5+." (PMID 31644426, 2019). "It is important to note, however, that the frequencies of circulating Tph cells in the peripheral blood of individuals with rheumatoid arthritis are also similarly low, even though they constitute on average more than 25% of all CD4+ T cells in synovial fluid or synovial tissue." (PMID 31270583, 2019). "A recent analysis of CD4+ T cells of patients with rheumatoid arthritis (RA) using mass cytometry and transcriptomics revealed a population of PD-1hiCXCR5−CD4+ T cells that is a distinct CD4+ T-cell subset, expands in the blood of RA patients, and contributes to RA pathogenesis." (PMID 30232328, 2018). "IL-16 is classically considered as a CD4+ T cell chemoattractant cytokine whose role in inflammation has been demonstrated in a handful of inflammatory diseases such as experimental autoimmune encephalomyelitis, rheumatoid arthritis, and allergy." (PMID 30555461, 2018). "IKZF2 deficient mice acquire an auto-inflammatory phenotype in later life similar to rheumatoid arthritis, with increased numbers of activated CD4+ and CD8+ T-cells, T-follicular helper cells, and germinal centre B-cells, which culminates in autoantibody production." (PMID 29059182, 2017). "Furthermore, ASH1L, SMAD3 and FOXP3 are all downregulated in CD4+ T cells from PBMCs of patients with rheumatoid arthritis, indicating the potential significance of ASH1L/SMAD3/FOXP3 pathway in human autoimmune pathogenesis." (PMID 28598443, 2017). "CD4+ T-cell counts could be a relevant biomarker of response to rituximab in rheumatoid arthritis and could be considered in making decisions about the timing of retreatment." (PMID 27793209, 2016). "We analyzed proportions of Th1 (CXCR3+), Th17 (CCR6+) and TfH (CXCR5+) cells within the CD4+CD45RO+ activated/memory population of a cross sectional group of seropositive Rheumatoid Arthritis patients on stable therapy (Cohort 1), compared to age and gender-matched healthy controls." (PMID 28004828, 2016). "Furthermore, CD4+PD-1+ T cells accumulate as unique anergic cells in rheumatoid arthritis synovial fluid." (PMID 24804191, 2014). "In rheumatoid arthritis, CD4+ Th cells play a pivotal role in the pathogenesis, as indicated by numerous genetic associations of the disease with polymorphisms in T cell related genes as well as by the clinical efficacy of CD28 co-stimulation and CD4 co-receptor blockade." (PMID 24667579, 2014). "In contrast to those isolated from healthy volunteers, CD4+CD28- T cells from rheumatoid arthritis patients may exhibit autoreactive properties." (PMID 25069714, 2014). "Similarly, IL-15 in combination with TNF-α can induce the expression of NKG2D in the CD4+NKG2D+ T cells found in patients with rheumatoid arthritis mentioned previously." (PMID 23056001, 2012). "Rheumatoid arthritis (RA) is a systemic autoimmune disease characterized by chronic inflammation throughout the body, particularly in diarthrodial joints, and inflammatory cell infiltration, including activated CD4+ T cells in peripheral blood." (PMID 22536280, 2012). "However, this concept was recently challenged by the discovery that DCIR can also be detected in CD4+ T cells found in the synovial tissue from rheumatoid arthritis (RA) patients." (PMID 21085612, 2010).
rheumatoid arthritis (continued). "In rheumatoid arthritis, increased frequencies of CD4+CD28null T cells in peripheral blood have previously been associated with extra-articular manifestations and human cytomegalovirus (HCMV) infection, but their presence in and contribution to joint manifestations is not clear." (PMID 17825098, 2007). "Expansion of CD4+CD28null T cells was initially described in patients with rheumatoid arthritis (RA), a chronic autoimmune disease of unknown etiology." (PMID 16207339, 2005). "The preferential expression of CD134 on synovial fluid CD4+ T cells from patients with rheumatoid arthritis, as has been demonstrated by others, indicates that also in humans auto-reactive T cells might be (transiently) marked by CD134." (PMID 15899047, 2005). "In this study, we explored the functional consequences of insulin signaling for the metabolism and phenotype of effector CD4+ T cells in blood and synovial tissue of patients with rheumatoid arthritis (RA)." (PMID 42185247, 2026). "The signature of these autoreactive CD4 T cells in the blood presented high similarity with the peripheral T helper cells (TPH) involved in the local adaptive immune response (B-helper function) in the synovium of patients with rheumatoid arthritis and in other tissues during autoimmunity." (PMID 39880819, 2025). "Furthermore, 1,25 (OH)2D3 can reduce the expression of inflammatory factors such as IL-17A, IL-17F, and IL-22, and decrease the number of CD4+ T cells and memory CD4+ cells in stimulated peripheral blood mononuclear cells from treatment-naive patients with early rheumatoid arthritis." (PMID 40630116, 2025). "Peripheral blood CD8+ and CD4+ T cells were isolated from patients with r‐axSpA (n = 128), PsA (n = 60), and rheumatoid arthritis (RA) (n = 74) and healthy donors (HDs) (n = 79)." (PMID 39835465, 2025). "Rheumatoid arthritis (RA) is a complex autoimmune disease in which the abnormal activation of memory CD4+ T cells plays a crucial role in its occurrence and progression." (PMID 40583347, 2025). "Atypical CD62L- naïve CD4 T cells have been described in rheumatoid arthritis (RA), where they correlate with disease flares and exhibit IL-1/IL-6/TNF-driven inflammatory signatures." (PMID 40661940, 2025). "Peripheral helper T (Tph) cells have been established, through intensive efforts to elucidate local immune responses in human rheumatoid arthritis (RA), as a CD4 subset intimately involved in acquired immunity in peripheral tissues." (PMID 37788648, 2024). "The expression of ENTPD1 in CD4+ and CD8+ T cells and B cells showed associations with disease activity indices in individuals with rheumatoid arthritis (RA)." (PMID 38612896, 2024). "The aim of this study was to combine deep T cell phenotyping with assessment of citrulline-reactive CD4+T cells in the pre-rheumatoid arthritis (RA) phase." (PMID 39557489, 2024). "ZNF334, a newly identified member of ZNFs, was initially identified as a molecular marker involved in rheumatoid arthritis (RA) and was extremely reduced in CD4 lymphocytes of RA." (PMID 36966142, 2023). "The human ortholog of this lncRNA is expressed in CD4+ and CD8+ T cells, and NK cells and their overexpression are linked to several inflammatory diseases like rheumatoid arthritis (RA), Hashimoto’s Thyroiditis (HT), and Sjogren’s syndrome." (PMID 37609636, 2023). "Although CD4+ T cells have been involved in pathogenesis of rheumatoid arthritis (RA), roles of DRs expressed on these cells in RA are poorly understood." (PMID 37237413, 2023). "Mechanistically, in rheumatoid arthritis (RA), naïve CD4+CD45RO- T produces fewer Foxp3 proteins, which results in the differentiation of naïve T cells into Th17 commitment, while leads to fewer Treg populations, which affects the Th17/Treg balance." (PMID 37936703, 2023).
rheumatoid arthritis (continued). "Indeed, accumulating evidence shows that senescent CD4+CD28− T lymphocytes are a common feature of chronic osteolytic pathologies such as rheumatoid arthritis, osteopenia, osteoporosis, and osteomyelitis and during the loss of orthopedic bone implants due to infectious causes." (PMID 35269683, 2022). "CD4+ T lymphocytes are capable of upregulating telomerase upon antigen stimulation, but lose telomerase activity with repetitive stimulations, which is especially seen in chronic diseases with excessive antigenic activation, such as rheumatoid arthritis, psoriasis or HIV." (PMID 35321714, 2022). "Rheumatoid arthritis is an autoimmune disease, and in the immune response to RA, the major players are CD4+ T-helper (Th) lymphocyte subsets." (PMID 36386123, 2022). "CD4+ T cells are central inflammatory mediators in the pathogenesis of autoimmune rheumatoid arthritis (RA), as they are one of the dominating cell types in synovial inflammation." (PMID 36114433, 2022). "Additionally, it could be shown in a mouse model of rheumatoid arthritis that joint regeneration after PTIC treatment was accompanied by a decrease in CD4+/IL17A+ T‐cell number and an increase in Tregs and CD4+/IFN‐γ+ T cells." (PMID 35604877, 2022). "A previous study demonstrated that glucose metabolism could be applied in conjunction with several inflammatory diseases like rheumatoid arthritis, in which rheumatoid arthritis fibroblast-like synoviocytes were cultured with CD4 T cells or T cell conditioned medium." (PMID 36247875, 2022). "This framework applied to rheumatoid arthritis (RA) revealed that activation of the TNF pathway in CD4+ T cells plays a vital role in RA etiology." (PMID 33557957, 2021). "CD4+ T cells mediate rheumatoid arthritis (RA) pathogenesis through both antibody-dependent and independent mechanisms." (PMID 34580414, 2021). "Besides chronic kidney diseases, rheumatoid arthritis is another pathological condition wherein there are several lines of evidence of premature aging of T cells, indicating a defective DNA repair mechanism in CD4+ naïve T cells." (PMID 33815398, 2021). "Effective tolerogenic intervention in Rheumatoid Arthritis (RA) will rely upon understanding the evolution of articular antigen specific CD4 T cell responses." (PMID 33986757, 2021). "Cholesterol plays an important role in regulating CD4+ T cells, and cholesterol accumulation is relevant to various diseases, such as rheumatoid arthritis (RA) and nonalcoholic steatohepatitis." (PMID 33505215, 2021). "CD4+T-lymphocytes are relevant in the pathogenesis of rheumatoid arthritis (RA), however, their potential involvement in early RA remains elusive." (PMID 32961930, 2020). "Recently, it has been found that lactate uptake via SLC5A12 results in pyruvate kinase M2/signal transducer and activator of transcription 3 (PKM2/STAT3)-mediated production of IL-17 in CD4+ T cells in rheumatoid arthritis (RA)." (PMID 33086598, 2020). "In rheumatoid arthritis (RA), increased number of CD4+ CD40L+ T cells expressing high CD40L transcripts was detected." (PMID 33297945, 2020). "Infiltration of memory CD4+ T cells in synovial joints of Rheumatoid Arthritis (RA) patients has been reported since decades." (PMID 30915067, 2019). "The abnormal activation of CD4+CD45RO+ memory T (Tm) cells plays an important role in the pathogenesis of rheumatoid arthritis (RA)." (PMID 29563614, 2019). "It has been shown that an anti-OPN antibody promoted apoptosis of activated T cells, particularly CD4+ T cells, by inhibiting activation of NF-κB in a model of rheumatoid arthritis (RA)." (PMID 29267211, 2017). "IL-17-secreting helper CD4 T cells (Th17 cells) constitute a newly identified subset of helper CD4 T cells that play a key role in the development of rheumatoid arthritis (RA) in its animal models." (PMID 28753982, 2017).
rheumatoid arthritis (continued). "We aimed to clarify the function of human IL-10-producing CD4+CD25−LAG3+ T cells (LAG3+ Tregs) and their association with rheumatoid arthritis (RA)." (PMID 28511719, 2017). "Data have been presented that CD8+CD28−CD56− T cells have suppressive activity in rheumatoid arthritis (RA), preventing the activation of naïve CD4+ T cells and inhibiting their effector function in vivo." (PMID 27965674, 2016). "Secondly, CD8+ T cells, which present antigen to molecules encoded by HLA class 1 alleles, were shown to predominate in PsA synovial fluid with a reversal of the CD4:CD8 ratio found in rheumatoid arthritis (RA)." (PMID 25948071, 2015). "The aim of this study was to investigate PD-1/PD-L1 involvement in the hyporesponsiveness of rheumatoid arthritis (RA) synovial fluid (SF) CD4 T cells upon stimulation by thymic stromal lymphopoietin (TSLP)–primed CD1c myeloid dendritic cells (mDCs)." (PMID 25433812, 2014). "In rheumatoid arthritis (RA), an other chronic and systemic autoimmune disorder, an unusual CD4+CD28−NKG2D+ population was detected in peripheral blood and synovial tissue." (PMID 25352848, 2014). "Therefore, the costimulatory signal triggered by the engagement NKG2D/NKG2D ligands coupled with suboptimal stimulation via TCR will induce important cytokine and cytotoxic responses, thereby self-perpetuating the CD4+NKG2D+ T cell autoreactivity in rheumatoid arthritis." (PMID 23947399, 2013). "The synovial membrane in patients with rheumatoid arthritis (RA) is characterized by an infiltrate of inflammatory cells, primarily CD4+ T cells." (PMID 24376610, 2013). "Rheumatoid arthritis (RA) is an autoimmune disease characterised by synovial proliferation in joints as well as infiltration of the synovial stroma by B cells, CD4+ helper T cells, plasma cells, and macrophages." (PMID 21816071, 2011). "However, this hypothesis seems unlikely because patients with rheumatoid arthritis display enriched CD4+CD25+CD45RO+ T cells not only in inflamed joints but also in peripheral blood." (PMID 19173720, 2009). "Reported data on frequency and activity of CD4+CD25high regulatory T cells in rheumatoid arthritis (RA) are conflicting." (PMID 19046457, 2008). "We previously demonstrated prolonged, profound CD4+ T-lymphopenia in rheumatoid arthritis (RA) patients following lymphocyte-depleting therapy." (PMID 15642146, 2005). "For instance, in rheumatoid arthritis, similar to pSS, CXCL10 increased the migration of inflammatory cells mediated through CXCR3 binding on CD4-positive T helper cells." (PMID 39436967, 2025). "In rheumatoid arthritis (RA) animal models, KMF demonstrated the efficacy in attenuating arthritis and decreased the proportion of CD4+ effector memory T cells (Tem) while increasing naïve and regulatory T cells (Tregs)." (PMID 40918131, 2025). "Recently, a new population of CD4+ T cells were identified with B cell helper function, called “Peripheral helper T” (Tph) cells, in inflammatory tissues of patients with rheumatoid arthritis (RA)." (PMID 41177827, 2025). "In rheumatoid arthritis (RA), high levels of serum toll-like receptor 2 (TLR2) and increased TLR2 expression on CD4+ T cells have been observed." (PMID 40963621, 2025). "■Inhibition of CD4+ and CD8+ T cell proliferation and IFN-γ, TNF-α, IL-6, and IL-17 release in rheumatoid arthritis;■Reduced iNOS expression induced by LPS in murine macrophages." (PMID 40298549, 2025). "In patients with rheumatoid arthritis, LINC00324 positively correlates with CD4+ T-cell expression and exacerbates inflammation by targeting miR-10a-5p through the NF-κB signaling pathway." (PMID 38530810, 2024). "In rheumatoid arthritis (RA), aberrant regulation of AMPK myristoylation leads to abnormal CD4 T-cell differentiation and triggers inflammation." (PMID 38485938, 2024).